RNU6-39P (RNA, U6 small nuclear 39, pseudogene)
Synonyms: RNU6-39
Gene: Small nuclear RNA gene on chromosome 18 (68,858,934 to 68,859,040, forward strand). Ensembl gene ENSG00000207072.
Homologues: Orthologues: chimpanzee U6 (99% identical), pig U6 (99% identical), tropical clawed frog U6 (99% identical), rat U6 (98% identical), guinea pig U6 (97% identical), rabbit U6 (97% identical), mouse Gm26285 (95% identical). Paralogues in human: RNU6-1 (98% identical), RNU6-2 (98% identical), RNU6-3P (98% identical), RNU6-4P (98% identical), RNU6-5P (98% identical), RNU6-6P (98% identical), RNU6-9 (98% identical), RNU6-12P (97% identical), RNU6-13P (97% identical), RNU6-16P (97% identical), RNU6-17P (97% identical), RNU6-18P (97% identical), and 1286 more.